GKAP1 (G kinase anchoring protein 1)
Description:
Regulates insulin-dependent IRS1 tyrosine phosphorylation in adipocytes by modulating the availability of IRS1 to IR tyrosine kinase. Its association with IRS1 is required for insulin-induced translocation of SLC2A4 to the cell membrane. Involved in TNF-induced impairment of insulin-dependent IRS1 tyrosine phosphorylation.
Synonyms: GKAP42; FKSG21
Tractability: PROTAC: ubiquitination databases record sites on it; its protein half-life has been measured.
Gene: Protein-coding gene on chromosome 9 (83,739,423 to 83,829,516, reverse strand). Ensembl gene ENSG00000165113.
Subcellular location: Golgi apparatus
Subcellular location (Human Protein Atlas): Centriolar satellite; Cytosol
Gene Ontology:
Molecular function: identical protein binding; protein binding
Biological process: positive regulation of insulin receptor signaling pathway; receptor guanylyl cyclase signaling pathway; signal transduction
Cellular component: Golgi apparatus
Genetic constraint (gnomAD): Loss-of-function variants: 7 observed, 16 expected, observed/expected ratio (o/e) 0.44, 90% interval 0.25 to 0.82. The upper end of that interval is the gene's LOEUF score, 0.82, which puts it in group 3 of 6, group 1 being the genes least tolerant of losing a copy. Missense variants: 113 observed, 135.51 expected, observed/expected ratio (o/e) 0.83, 90% interval 0.71 to 0.98. Synonymous variants: 41 observed, 46.29 expected, observed/expected ratio (o/e) 0.89, 90% interval 0.69 to 1.15.
Homologues: Orthologues: chimpanzee GKAP1 (100% identical), macaque GKAP1 (99% identical), guinea pig GKAP1 (93% identical), dog GKAP1 (93% identical), pig GKAP1 (89% identical), mouse Gkap1 (88% identical), rat Gkap1 (87% identical), rabbit GKAP1 (86% identical), tropical clawed frog gkap1 (64% identical), zebrafish gkap1 (61% identical).
Diseases named in the same sentence as GKAP1 in open-access papers:
GKAP1 is named in the same sentence as 3 diseases in open-access papers, as found by Europe PMC text mining. Sharing a sentence is not in itself a finding about the gene and the disease. The quoted sentences say what the papers report.
Insulin resistance (2 papers, 2022 to 2023). Increased resistance towards insulin, that is, diminished effectiveness of insulin in reducing blood glucose levels. "Tumor necrosis factor (TNF) is mainly secreted by macrophages and can induce insulin resistance through inhibition of Insulin receptor substrate 1 (IRS1), tyrosine phosphorylation and G kinase-anchoring protein 1 (GKAP42) degradation in adipocytes." (PMID 36457705, 2022).
tumour (1 paper, 2024). "Patient #3, a 3-year-old female with GKAP1::NTRK2-fused LGG in the right thalamus and 3rd ventricle, underwent adjuvant larotrectinib treatment for residual tumour." (PMID 39014476, 2024).
GKAP1 also shares sentences with these, for which no sentence is quoted: oligospermia (1 paper).